PCSK9 (proprotein convertase subtilisin/kexin type 9)
Diseases named in the same sentence as PCSK9 in open-access papers (continued):
Sharing a sentence is not in itself a finding about the gene and the disease.
Insulin resistance (continued). "Very recently, in severely obese patients undergoing bariatric surgery, our group confirmed a pivotal role played by adipose tissue and insulin resistance on PCSK9 levels." (PMID 33143700, 2020). "The link between PCSK9 and insulin resistance has been confirmed in obese individuals undergoing gastric bypass." (PMID 33143700, 2020). "Depression was associated also with the HOMA-IR (homeostatic model assessment index of insulin resistance), 11% of this effect operating indirectly via PCSK9." (PMID 33143700, 2020). "The role of SREBP-1c in the regulation of PCSK9 levels has also been observed in humans, where PCSK9 is positively correlated with insulin resistance, liver steatosis, and very low-density lipoprotein-triglyceride (VLDL-TG) levels." (PMID 30634533, 2019). "Even if most findings suggest a direct correlation of PCSK9 with abnormal glucose metabolism and insulin resistance, some studies suggest an opposite relation similar to that found in the present work." (PMID 31672148, 2019). "The effects of PCSK9 rs11591147 were also very close to null for these measures, including for glycolysis related metabolites and markers of insulin resistance." (PMID 30524137, 2018). "Repressing PCSK9 expression can control serum lipids and thus, ameliorate insulin resistance to some extent." (PMID 26833058, 2016). "Plasma PCSK9 is associated to LDL-C and to a lesser extent plasma triglycerides and insulin resistance." (PMID 23298392, 2013). "Under these specific nutritional conditions, PCSK9 concentrations were positively correlated with insulin resistance, liver steatosis and VLDL-TG concentrations." (PMID 23298392, 2013). "The main purpose of this study was to verify whether PCSK9 expression in vascular smooth muscle cells (VSMC) is influenced by insulin resistance and high glucose (HG)." (PMID 39940773, 2025). "Similarly, stratification according to insulin resistance (HOMA-IR < 2.0 vs. ≥2.0) demonstrated significant differences in PCSK9 and CRP concentrations, Castelli indices I and II, and the TyG index." (PMID 41516208, 2025). "In experiments with cultured aortic VSMC from LZR and OZR, we were able to identify important and new findings on the relationships between PCSK9 expression and two pathognomonic conditions underlying metabolic and vascular disorders related to T2DM: insulin resistance, and hyperglycemia." (PMID 39940773, 2025). "The main purpose of this study was to verify whether PCSK9 expression in VSMC is affected by the insulin-resistance state and high glucose exposure." (PMID 39940773, 2025). "The determination of serum glucose and liver glutamate oxaloacetate transaminase (GOT) revealed elevated levels of both markers in comparison to standard values (GOT ~48 U/L; glucose ~136 mg/dL) in wild-type mice treated with PCSK9/PD, indicating insulin resistance and disturbed liver function." (PMID 39409049, 2024). "Additionally, further studies are warranted to explain the mechanism of resistance exercise training in decreasing the PCSK9 level, especially via the proposed mechanism such as Annexin A2, adiponectin, and insulin resistance measured with HOMA-IR." (PMID 37946122, 2023). "One possible explanation could be that treatment with anti-PCSK9 mAb determines a detectable improvement in hepatic insulin sensitivity only in those with a worse metabolic pattern, higher insulin resistance and BMI." (PMID 37324254, 2023). "Furthermore, treatment with ANP in human cultured adipocytes reduced insulin-induced PCSK9 expression, especially in the context of hyperglycemia, simulating a clinical condition of insulin resistance/T2DM in our recent experimental study." (PMID 36009507, 2022).
Insulin resistance (continued). "Collectively, we describe a novel mechanism for PCSK9 expression in adipose tissue that could mediate statin-impaired adipose insulin resistance." (PMID 36558473, 2022). "It is, however, unknown if PCSK9 participates in adipocyte insulin resistance occurring as a result of statin use." (PMID 36558473, 2022). "In addition to regulating lipid transport, PCSK9 has many other effects on cell functions, such as in the processes of viral infection, insulin resistance, development of the central nervous system, tumor apoptosis and tumor immunity." (PMID 33789749, 2021). "Previous data suggested that insulin resistance and subsequent hyperinsulinemia could enhance PCSK9 expression and increased plasma levels of PCSK9 were related to poor glycemic control in DM." (PMID 33023603, 2020). "Besides, it has been demonstrated that insulin resistance plays a pivotal role in PCSK9 homeostasis in severely obese patients." (PMID 33023603, 2020). "Furthermore, PCSK9 levels correlate positively with markers of glycemia such as fasting glucose and insulin resistance in adults and adolescents." (PMID 30899674, 2019). "Insulin resistance has been reported to associate with diminished remnant clearance by impairing the HSPG structure via modulation of hepatic SULF2 expression and by altering LDL receptor via PCSK9." (PMID 27686975, 2016). "As such, PCSK9 might be a promising target in ameliorating lipid and glucose metabolism disorders and improving insulin resistance." (PMID 26833058, 2016). "In addition, insulin resistance has been observed to cause an increase in hepatocyte PCSK9 transcription, so the increase in PCSK9 levels in patients with PTDM may be just a sign of insulin resistance from other causes." (PMID 35683632, 2022). "PCSK9 deficiency is associated with impaired glucose tolerance in mice, which appears to be the consequence of decreased insulin secretion from the pancreas rather than insulin resistance." (PMID 36558473, 2022). "Interestingly, they also found signs of insulin resistance in the PCSK9 knock-out animals." (PMID 33692700, 2021). "Therefore, the relationship between insulin resistance and PCSK9 levels may be affected by gut microbiota dysbiosis." (PMID 33302966, 2020). "Moreover, insulin resistance and decreased concentration of vitamin D were linked to adverse metabolic profile, while smoking appeared to exacerbate oxidative stress and inflammation rather than directly influencing PCSK9 levels." (PMID 41516208, 2025). "Also, in some other studies, LOF PCSK9 variants InsLEU (1745 healthy French-Canadian individuals) and R46L (5972 French individuals) did not demonstrate an effect on glucose homeostasis and insulin resistance." (PMID 38028979, 2023). "Insulin resistance contributes to an increase in circulating LDL cholesterol levels by upregulating hepatic lipase and protein convertase subtilisin/kexin type 9 (PCSK9)." (PMID 33810315, 2021). "Protective effects of PCSK9 inhibitions against NAFLD and insulin resistance have been reported in recent studies." (PMID 34876018, 2021). "Conversely, in the insulin-resistance state, HG is not able to further influence PCSK9 already basally upregulated, even though PCSK9 inhibitors preserve their ability to exert inhibitory effects on PCSK9 expression." (PMID 39940773, 2025). "Since hyperglycemia plays a significant role in the development of T2DM complications and the condition of insulin resistance is a common feature of obese T2DM patients, we aimed to clarify whether high glucose influences VSMC PCSK9 expression." (PMID 39940773, 2025).
Insulin resistance (continued). "When the cholesterol levels overwhelm the ER, like in PCSK9-GOF, a shift of excessive cholesterol into the ER induces stress and misfolded proteins, which may in turn induces insulin resistance, inflammation, and kidney damage." (PMID 39094771, 2024). "Those authors explained their findings by suggesting that the relationship between PCSK9 and insulin resistance may occur through mechanisms that are independent of body fat distribution." (PMID 35454343, 2022).
Hypertension (61 papers, 2014 to 2025). The presence of chronic increased pressure in the systemic arterial system. "Despite the plethora of studies on PCSK9 mutations in cholesterol metabolism, its role in the etiology of hypertension remains poorly understood." (PMID 25904937, 2015). "Using genomic data assayed on the Affymetrix 6.0 array (n = 1199) and the Illumina HumanExome Beadchip (n = 1966) from the Hypertension Genetic Epidemiology Network (HyperGEN), we tested the association of PCSK9 polymorphisms with blood pressure." (PMID 25904937, 2015). "We found that the PCSK9 R93C variant might negatively interact with hypertension and smoking, resulting in reduced impact of other CHD risk factors on PMI." (PMID 35480303, 2022). "If PCSK9 is truly associated with hypertension, then it is reasonable to speculate it would associate with DBP at younger ages and SBP at older ages." (PMID 25904937, 2015). "It has been speculated that GOF mutation of PCSK9 will therefore reduce membrane-bound ENaC expression leading to less sodium reabsorption and potentially less hypertension in the long-term." (PMID 25600226, 2015). "Adiponectin, an adipokine known for its antihypertensive properties, further underscores the potential of PCSK9 as an early biomarker for detecting hypertension." (PMID 40354375, 2025). "The ASCVD group was older and had a higher incidence of hypertension, increased use of antihypertensive medications, hypoglycemic agents, statins or PCSK9 inhibitors, antiplatelet agents, and anticoagulants, alongside elevated MSBP and HbA1c levels." (PMID 41019429, 2025). "The positive correlation between PCSK9 and MyBPC3 in patients with diagnosed hypertension and the similar direction of changes in the levels of these proteins in other groups of men indicate a significant association between them." (PMID 40136460, 2025). "PCSK9 is associated with increased serum levels of LDL-C and oxidative factors in pregnant women that increase the risk of endothelial damage and hypertension in preeclampsia." (PMID 38077944, 2023). "After controlling for confounding variables (sex, age, body mass index, arterial hypertension, statin dose and PCSK9 inhibitor dose), all correlations were still significant except the association between change in GlycB and change in triglycerides." (PMID 36768645, 2023). "In another model, PCSK9 level and hypertension were found to be independent predictors of E/e′ (ie, diastolic dysfunction)." (PMID 38094682, 2023). "In two secondary analyses, after stratification of FH patients according to smoking and hypertension respectively, similar results were obtained after 6 months of PCSK9-i treatment." (PMID 35928226, 2022). "Similar or slightly favorable economic value of the PCSK9 inhibitor was observed in several subgroups, including female, DM or hypertension with MI." (PMID 33935749, 2021). "In a study involving PCSK9 D374Y transgenic minipigs with elevated cholesterol levels, researchers observed a notable increase in coronary atherosclerosis and the persistent formation of sizable fibroatheromas, leading to cephalad hypertension." (PMID 40354375, 2025). "Additionally, PCSK9's influence on hypertension, peripheral artery disease, and kidney diseases underscores its multifaceted role in vascular health and its promise as a target for mitigating a range of cardiovascular complications." (PMID 40354375, 2025). "In one unique case, an individual bearing a PCSK9 LOF mutation barely expressed PCSK9 and did not manifest hypertension." (PMID 39139638, 2024). "Therefore, it can be claimed that PCSK9 was considered an important factor in the changes of oxidative stress and hypertension in preeclampsia." (PMID 38077944, 2023).
Hypertension (continued). "I propose that several new parameters (NO, cfDNA, MPO, PCSK9, MyBPC3, microRNA, TAS, Pb, and Cd) with prognostic and/or predictive potential should be included in screening to confirm the need for the extensive testing of middle-aged men by healthcare professionals due to the risk of hypertension." (PMID 40136460, 2025). "In two secondary analyses, after stratification of FH patients according to smoking and hypertension respectively, we observed a significant reduction of serum CLC in smokers and hypertensive patients after 6 months of PCSK9-i treatment." (PMID 35928226, 2022). "Meanwhile, the cardiovascular field has introduced new anticoagulants (e.g., DOACs), PCSK9 inhibitors, and SGLT2 inhibitors, alongside updated guidelines for hypertension and heart failure, such as stricter blood pressure targets and recommendations for novel therapies." (PMID 41141353, 2025). "The observation of the highest levels of PCSK9 in men diagnosed with hypertension at the same time as the highest levels of total cholesterol and LDL cholesterol in this group indicates its potential role as an early biomarker of hypertension." (PMID 40136460, 2025). "A higher plasma PCSK9 was observed in subjects with hypertension (246.1 ± 53.8 vs. 207.6 ± 57.0, p = 0.03) and in non-smoking subjects (221.8 ± 58.6 vs. 185.8 ± 43.3, p = 0.043)." (PMID 36324757, 2022). "Even after further adding BMI, family history of CAD, hypertension, smoking status, drinking status, triglycerides, LDL-C, HDL-C, FPG, and HbA1c into the multivariate linear regression model, the positive relation of PCSK9 levels with NFS remained significantly different (β = 0.073, P = 0.001)." (PMID 34996457, 2022).
Hepatic steatosis (47 papers, 2013 to 2026). Steatosis is a term used to denote lipid accumulation within hepatocytes. "Clinical trials and animal studies using PCSK9 inhibitors have suggested potential benefits in reducing liver steatosis, inflammation, fibrosis, and cardiovascular risk." (PMID 39969435, 2025). "PCSK9 R46L variant is also associated with a twofold increased prevalence of hepatic steatosis and higher epicardial adiposity in human carriers of the PCSK9 R46L mutation." (PMID 38907775, 2025). "Two recent studies have shown circulating PCSK9 was associated with hepatic steatosis and PCSK9 rs11591147 loss of function mutation had protective effect against hepatic steatosis." (PMID 34876018, 2021). "In multivariate regression model, AG + GG genotypes of PCSK9 rs505151 were associated with moderate to severe hepatic steatosis in liver transplant recipients (OR 5.747; 95% CI 1.086–30.303; P value = 0.040)." (PMID 34876018, 2021). "In our study, liver transplant recipients with AG + GG variants of PCSK9 rs505151 conferred an increased risk for higher degrees of hepatic steatosis as assessed by CAP." (PMID 34876018, 2021). "In morbidly obese patients hepatic PCSK9 protein was reduced in the patients with fatty liver whereas associations with hepatic inflammation and hepatocyte ballooning did not exist." (PMID 33461570, 2021). "It has been reported that circulating PCSK9 was associated with severity of hepatic steatosis, ballooning and fibrosis stage." (PMID 34876018, 2021). "Circulating PCSK9 has been found to be significantly associated with hepatic steatosis grade, necroinflammation, ballooning, and fibrosis stage." (PMID 28827398, 2017). "In accordance with a potential link between PCSK9 and liver steatosis, we recently described a positive association between PCSK9 and gamma-glutamyl transferase levels, a marker of hepatic steatosis, in type 2 diabetic patients." (PMID 23298392, 2013). "Previous studies have suggested that PCSK9 deficiency confers resistance to hepatic steatosis." (PMID 39969435, 2025). "On the other hand, early investigations on the effect of PCSK9-R46L showed that carriers of this variant displayed a two-fold increase in the prevalence of hepatic steatosis, while more recent data suggest that the PCSK9-R46L variant is protective against liver damage in patients with NAFLD." (PMID 35323658, 2022). "Notably, 64% of carriers of the PCSK9 R46L variant also displayed hepatic steatosis, which reflected a 2-fold higher incidence compared to non-mutant carriers." (PMID 35162992, 2022). "Altogether these data suggest that PCSK9 deficiency (primarily genetic) could promote hepatic steatosis, at least in preclinical models with mice." (PMID 33692700, 2021). "Genetic variations in TM6SF2 rs58542926 and PCSK9 rs505151 might be associated with hepatic steatosis in liver transplant recipients." (PMID 34876018, 2021). "Our results revealed that TM6SF2 rs58542926 and PCSK9 rs505151 variants might be associated with hepatic steatosis after liver transplantation." (PMID 34876018, 2021). "Of note, hepatic PCSK9 expression was also associated with liver steatosis." (PMID 33920491, 2021). "However, whether loss-of-function PCSK9 mutant carriers are also protected from liver steatosis is less certain." (PMID 35162992, 2022). "In the present study, a positive relationship between NFS and PCSK9 was found, which was supported by Lebeau’s team who used hepatocyte-specific PCSK9-knockout mice and showed that PCSK9 blockade or deficiency conferred resistance to liver steatosis to repair hepatic damage." (PMID 34996457, 2022). "In NAFLD, PCSK9 contributes to hepatic steatosis through receptor-dependent and -independent pathways, upregulating genes associated with lipid synthesis and cholesterol biosynthesis." (PMID 40764605, 2025).